CRP (C-reactive protein)
Diseases named in the same sentence as CRP in open-access papers (continued):
Sharing a sentence is not in itself a finding about the gene and the disease.
iron deficiency (continued). "Most epidemiological studies on the interplay between iron deficiency and malaria risk classify individuals as iron-deficient or iron-replete based on inflammation-dependent iron markers and adjustment for inflammation by using C-reactive protein (CRP) or α-1-acid glycoprotein (AGP)." (PMID 30537973, 2018). "Consistently, an inverse association of CRP levels with magnesium intake or serum magnesium was reported in several epidemiological studies, which suggested that magnesium deficiency might be involved in the development of low chronic inflammatory syndrome, which can modulate T2D25." (PMID 28986547, 2017). "We therefore performed a second analysis using a single definition for iron deficiency that disregarded the effects of malaria on ferritin levels but only stratified the ferritin levels by the inflammatory response, i.e. plasma ferritin<12μg/ml if CRP<10mg/ml or ferritin<30μg/ml if CRP≥10mg/ml." (PMID 21103365, 2010). "Iron deficiency (as defined by MCV, ferritin, CRP and soluble transferrin receptor serum levels) and low hemoglobin levels simultaneously were detected in 48 patients (n = 48/155; 31%)." (PMID 40759730, 2025). "The BRINDA project has shown that ferritin correction for CRP (and AGP where available) substantially alters iron deficiency prevalence estimates, particularly in high‐inflammation settings." (PMID 40968580, 2025). "Laboratory investigations were notable for C-reactive protein (CRP) of 100 mg/L and iron deficient anaemia (haemoglobin (Hb) of 83 g/L and transferrin saturation of 6%)." (PMID 37349797, 2023). "Five nodes were identified as relevant to kidney function via analysis of the hub neighborhoods: iron deficiency, PTH, urea, uric acid, and C-reactive protein." (PMID 36230609, 2022). "We previously reported that correcting for inflammation, based on CRP and AGP levels, modified the estimated levels of the iron status and prevalence of iron deficiency among pre-schoolers in a similar setting of western Kenya." (PMID 36211493, 2022). "Iron deficiency (ZPP > 70 μmol/mol heme) was present in 118/1,240 (9.5%) students with a normal hemoglobin genotype, all of whom had plasma ferritin <15 ng/ml and CRP <5 mg/L." (PMID 31448286, 2019). "Overall, the prevalence of iron deficiency increased in both Kisumu and Nairobi groups after using the IRC approach to adjust for CRP or AGP." (PMID 30781529, 2019). "The acute phase proteins CRP and AGP are commonly used to compensate for the effect of inflammation when ferritin levels are used to detect iron deficiency." (PMID 30537973, 2018). "Overall, 29/180 patients (16.11%) had magnesium deficiency and 24/193 (12.43%) calcium deficiency, 18.28% of patients (32/175) had PTH levels above the upper normal range and 70/115 (60.86%) had CRP levels above the upper normal range." (PMID 30323223, 2018). "The elevated CRP group had iron and red blood cell (RBC) profiles characteristic of chronic immune stimulation (CIS), and the normal CRP group, profiles of true iron deficiency." (PMID 21547258, 2011). "CRP can stimulate the synthesis of ferritin and promote its combination with intracellular iron, thus reducing the serum iron content in the body and increasing the risk of CRA and iron deficiency." (PMID 38562035, 2024). "Correcting for inflammation using CRP and/or AGP significantly improved the diagnostic accuracy of ferritin levels in patients with IBD, highlighting the challenge posed by inflammation when assessing iron deficiency." (PMID 39061651, 2024). "The literature emphasizes the importance of evaluating blood markers associated with a reduced inflammatory state (such as the neutrophil-to-lymphocyte ratio, CRP, fibrinogen, and various cytokines and adipokines) for the early detection of inflammation related to nutritional disorders." (PMID 39768291, 2024).
iron deficiency (continued). "s-CRP and ECW% increased the likelihood of nutritional risk, whereas independent biomarkers such as PA and s-albumin ≥ 3.8 g/dL were shown to reduce the risk of nutritional disorders in elderly HD patients." (PMID 38140295, 2023). "In the present study, biochemical markers were not included due to lack of feasibility to obtain serum ferritin and C-reactive protein as primary indicators for iron deficiency." (PMID 35684114, 2022). "Compared to sTfR, there was no substantial difference in the discriminatory ability of ferritin to identify iron deficiency (i.e., IDA or ACD/IDA) in patients with low inflammatory activity (CRP levels less or equal to the median of serum CRP, i.e., 24.1 mg/l)." (PMID 36275413, 2022). "Measurement of C-reactive protein was performed to exclude false-negative result of iron deficiency." (PMID 36333424, 2022). "However, in our MINDI cohort, 94% of lactating women including those with the highest CRP concentrations had ferritin values < 70 μg/L, suggesting that in the MINDI cohort, this cut-off would overestimate iron deficiency." (PMID 36079755, 2022). "In our patients, the relationships between iron deficiency and CRP levels were no longer significant in the multiple regression model." (PMID 33026590, 2021). "Functional iron deficiency is defined by low circulating iron levels and TSAT <20% but with normal or increased serum ferritin levels (>100 μg/L) along with systemic markers of inflammation (C-reactive protein [CRP] and interleukin 6 [IL-6])." (PMID 33426933, 2021). "Compared with the non-iron deficiency group, patients with iron deficiency had lower Hb and higher CRP levels." (PMID 32901103, 2021). "The higher ferritin cut-off approach performed quite well with CRP in comparison with the IRC approach, though the latter was more consistent in its performance, meaning that it always gave the highest prevalence estimates of iron deficiency." (PMID 30781529, 2019). "Children with high levels of CRP had higher hepcidin concentration, but this difference was statistically significant only in those without iron deficiency." (PMID 31500264, 2019). "iron deficiency without inflammation (ferritin< 14 μg/L and CRP < 10 mg/L) and serum ferritin were assessed." (PMID 30249193, 2018). "We used a high ferritin cut-off of < 70 μg/L for iron deficiency in women with CRP ≥ 10 μg/mL, allowing for inflammation, as well as the lower cut-off < 15 μg/L with CRP < 10 μg/L to include those without inflammation." (PMID 29166928, 2017). "Compared to children with sTfR < 8.3 mg/L, children with elevated sTfR were younger and more likely to be male and have malaria, inflammation (elevated CRP and/or AGP), iron deficiency (defined either as inflammation-adjusted ferritin < 12 μg/L or BIS < 0 mg/kg), and the HbSS genotype." (PMID 28671630, 2017). "Although prevalence of iron deficiency in absolute terms varied according to the CRP cut-off used, sensitivity analyses showed that trends and trial arm differences in iron deficiency were similar irrespective of CRP level." (PMID 29166928, 2017). "Iron deficiency in the absence of inflammation (normal CRP and calprotectin) is characterized by low ferritin level <30 ng/mL (1 ng/mL of serum ferritin corresponds to approximately of stored iron)." (PMID 25646159, 2014). "While iron deficiency (based on a definition with ferritin and CRP) is associated with a marked decreased risk of malaria in pregnancy, this association was not present among any of the other biomarkers of iron deficiency." (PMID 24551064, 2014). "As ferritin is an acute phase protein, normal ferritin levels do not exclude significant iron deficiency in patients with increased CRP or significantly increased calprotectin." (PMID 25646159, 2014). "In patients without severe iron deficiency and with normal CRP levels, hepcidin-25 was correlated with ferritin, and inversely correlated with TF and mean corpuscular volume (MCV) values." (PMID 23433094, 2013).
iron deficiency (continued). "In order to avoid the confounding effect of acute inflammation and severe iron deficiency, we analyzed whether the TMPRSS6 A736V polymorphism influenced iron parameters and erythropoiesis in patients with CRP < 1 mg/dl and ferritin > 30 ng/ml." (PMID 23433094, 2013). "Thus, iron deficiency is linked to C-reactive protein (CRP) and elevated IgE levels irrespective of the cause." (PMID 36698466, 2022). "Iron deficiency could not be accurately measured because many children had very elevated ferritin and CRP levels, suggesting inflammation that altered ability to use ferritin as a marker of iron deficiency." (PMID 32901609, 2020). "When combining low ferritin with ferritin 30–100 μg/L among those with elevated CRP to a model, iron deficiency could not be excluded among a higher proportion of cases, compared to controls." (PMID 32541236, 2020). "However, there is currently no consensus on when to include CRP in the diagnostic work-up for iron deficiency or what thresholds should be applied." (PMID 29744352, 2018). "Second, due to limitations in the amount of blood drawn from small children, C-reactive protein level and other laboratory tools such as transferrin receptors were not examined in our study, thus, the true incidence of iron deficiency in our population remained uncertain." (PMID 29559671, 2018). "Only 76 patients had no inflammation (CRP <5 mg/L) and no iron deficiency (TSAT >20%)." (PMID 28747155, 2017). "In patients without acute inflammation and overt iron deficiency (C reactive protein <1 mg/dl and ferritin >30 ng/ml; n = 86), hepcidin was associated with lower mean corpuscular volume (p = 0.002), suggesting that it contributed to iron-restricted erythropoiesis." (PMID 23433094, 2013). "Additionally, the absence of C-reactive protein assessment was another limitation, which would have ruled out the presence of infection and, thus, validate the actual level of iron deficiency in the women studied." (PMID 20824979, 2010). "When CRP was >3 mg/L, iron deficiency could not be excluded if ferritin was <100 μg/L." (PMID 32541236, 2020). "In similar resource-poor, high-infection burden regions, CRP alone may be sufficient to adjust for inflammation when using the IRC approach, but there is value in using AGP whenever possible, as it does lead to higher estimates of the prevalence of iron deficiency." (PMID 30781529, 2019). "The other previous study of oral sodium ferrous citrate in hemodialysis patients with iron deficiency reported a decrease in iFGF23, cFGF23, dose of ESA, and CRP levels without changes in serum phosphorus." (PMID 38402503, 2024). "Adiposity enhances low iron status and increases CRP and ferritin levels in the non-CKD population; thus, adiposity-related inflammation can cause functional iron deficiency." (PMID 29103135, 2018). "The iron panel does not demonstrate iron deficiency, and the ESR/CRP is nonelevated." (PMID 40104156, 2025). "However, adjusting for malaria alone, or adjusting for malaria in addition to CRP and AGP, did not significantly change the prevalence estimates of iron deficiency." (PMID 39450524, 2024). "Our study did not include C-Reactive Protein measurement to assess infection or inflammation in these patients with low hemoglobin and high ferritin; however, the high median TSAT level is not in favor of functional iron deficiency and makes inflammation less plausible." (PMID 36303122, 2022). "However, we did not measure CRP and ferritin in students with a normal ZPP and it is possible that some students with earlier stages of iron deficiency may have been missed." (PMID 31448286, 2019). "Therefore, this study will focus on correlating serum ferritin with C-reactive protein (CRP) and its association with iron and BMI, and to find out whether, it is safe to keep using serum ferritin as a true measure of iron deficiency in overweight and obese people or not." (PMID 28116148, 2016).
malaria (214 papers, 2005 to 2026). Malaria is a serious and sometimes fatal disease caused by a parasite that commonly infects a certain type of mosquito which feeds on humans. "This seems to mirror our findings from high endemicity settings, wherein malaria was associated with increased ferritin only at higher CRP levels." (PMID 39450524, 2024). "We identified a comparable European cohort of 765 febrile international travellers: here, elevated CRP levels were independently associated with malaria." (PMID 37889376, 2024). "Few patients with malaria (6/50) and bacterial infection (12/49) had CRP levels < 20mg/L, the threshold most commonly used to eliminate viral causes with quantitative CRP analysis." (PMID 37478118, 2023). "In line with this, CRP has previously been shown to associate with the degree of parasitaemia, as well as other markers of severe malaria." (PMID 37087435, 2023). "Clinical specimens (blood, stool and urine) collected from 396 febrile children (axillary temperature of ≥ 37.5 °C) were analyzed with rapid diagnostic tests (malaria and CRP) and microbiology culture to establish the possible cause of fever." (PMID 36536340, 2022). "A combined malaria/CRP rapid diagnostic test would be a breakthrough for rural settings, though the determination of a valid cut-off value for CRP will be challenging." (PMID 33647009, 2021). "In the parent trial, malaria during pregnancy was associated with elevation of inflammatory mediators including sTNFRII, CRP, and CHI3L1 across pregnancy." (PMID 34582452, 2021). "Recent illness and inflammation were associated with poorer z‐scores in all domains (e.g., 0.06 higher gross motor z‐score per 1 SD increase of ln (CRP)), whereas a positive malaria test was associated with poorer gross motor z‐scores only." (PMID 31823490, 2020). "Malaria associated inflammation as represented by CRP (geometric mean CRP, mg/l, (n) 1.3 [95% CI 1.0:1.7] without parasitaemia; 9.2 [7.8:10.9] with parasitaemia; relative risk: 1.97 [1.66:2.29], P < 0.001) upregulates hepcidin." (PMID 31771607, 2019). "By comparison, in a meta-analysis from non-malaria endemic countries, raised plasma CRP was associated in mid-gestation with a risk ratio of 1.53 (95% CI 1.22:1.90) for spontaneous PTB." (PMID 31060615, 2019). "There was a consistent and significant association between elevated CRP and malaria with all 3 surveys reporting data that revealed significant results (with ORs ranging from 2.9 to 3.9, P < 0.05)." (PMID 28615263, 2017). "Our results show that RBP was associated with malaria independently from CRP and AGP, which was consistent with a recent study that also examined this relation." (PMID 28615251, 2017). "There was a consistent and significant association between elevated CRP and recent fever and malaria in all 5 surveys with relevant data." (PMID 28615263, 2017). "In PSC, elevated CRP was only associated with fever and malaria, whereas elevated AGP was associated with fever, cough, diarrhea, and malaria in a majority of data sets." (PMID 28615263, 2017). "Malaria was marginally associated with inflammation (defined as elevated CRP and/or AGP, Rao-Scott chi-square P = 0.07)." (PMID 28671630, 2017). "At 12 months, ferritin, vitamin B12 and CRP levels as well as low socio-economic status were associated in univariate analysis with increased malaria risk with regard to both the risk of having a positive smear and P. falciparum parasite density." (PMID 26866471, 2016). "We conducted a case-control study to explore the association between subclinical malaria and C-reactive protein (CRP), an established biomarker of inflammation." (PMID 27386859, 2016). "Malaria is associated with elevated CRP and the data from this study as well as the limited previous evidence suggest this is also the case for procalcitonin." (PMID 26558692, 2015). "In Brazilian populations, IL-10 and CRP are an important marker of acute malaria caused by P. vivax." (PMID 25309052, 2014).
malaria (continued). "The use of principal component analysis and cluster analysis associated increased levels of IL-6, TNF-α, IL-10, and CRP and low levels of IL-17A predominantly with individuals with malaria alone and coinfected individuals." (PMID 25309052, 2014). "In order to evaluate the diagnostic accuracy of copeptin for severe malaria, the performance of copeptin was compared to that of sodium, CRP, lactate and procalcitonin." (PMID 22221299, 2012). "The FcγRIIa has been shown to have a higher affinity for CRP if the R131 allele of the receptor is present, the same allele that in some studies has been related to protection against malaria." (PMID 19545442, 2009). "The sample size in this study was probably too small for making any firm conclusions, but the results strongly indicate a need for further studies on the impact of CRP in relation to susceptibility to malaria." (PMID 19545442, 2009). "In conclusion, this study has demonstrated a marked difference in CRP genotype frequencies in two independent samples of Africans with low susceptibility to malaria as compared to sympatric ethnic groups." (PMID 19545442, 2009). "One such marker, CRP, has been shown to occur in high levels in children infected with malaria, and this could be due to injury caused by the parasite." (PMID 40277833, 2025). "Patients with viral cause of fever had a CRP level of 1 mg/dl, those with bacterial acute undifferentiated febrile illness 3.5 mg/dl and undiagnosed acute undifferentiated febrile illness 2.5 mg/dl compared with a CRP of 9.1 mg/dl in malaria patients." (PMID 37889376, 2024). "Finally, in order to understand the influence of markers of HIV immunodeficiency and immune activation (HIV-1 VL, CD4+ counts and CRP) on malaria-specific antibodies, the concentrations of these markers were correlated with these antibody levels." (PMID 31470903, 2019). "The intention was to find out if CRP could help in distinguishing clinical malaria manifestations from other causes." (PMID 30080904, 2018). "Similarly, increased CRP levels were strongly associated with clinical malaria, defined as parasitemia > 5000 parasites/μl (OR 16.5 [CI 2.2–121], p<0.001)." (PMID 30080904, 2018). "Malaria and wasting were strongly associated with both elevated CRP and elevated AGP." (PMID 28615263, 2017). "Second, there is a possibility of confounders and reverse causality, whereby for instance other causes of fever or elevated CRP might trigger relapse of malaria parasites." (PMID 27386859, 2016). "In case of documented dengue, an elevated CRP level may lead to seek an associated diagnosis such as malaria or bacterial infection." (PMID 24069477, 2013). "An elevated CRP (>5 mg/L) was significantly associated with malaria (p<0.001)." (PMID 24069477, 2013). "Finally, the CRP level was a useful, sensitive and simple tool to identify patients at low risk of malaria during DF epidemics and to guide the decision of parasitological examination, without replacing the thick smear." (PMID 24069477, 2013). "We found that an elevated CRP level was independently associated with malaria." (PMID 24069477, 2013). "Moreover, using only the CRP level turned to be a useful biomarker to discriminate feverish patients at low risk of malaria in an area where both infections exist." (PMID 24069477, 2013). "The present study demonstrates striking differences regarding CRP single nucleotide polymorphisms between sympatric ethnic groups, which may contribute to the differences in their susceptibility to malaria." (PMID 19545442, 2009). "The results suggest that the -286 CRP polymorphism may be a contributing factor in the lower susceptibility to malaria seen in the Fulani group." (PMID 19545442, 2009). "This study indicate that CRP may play an important role in the immune responses to malaria, and that the -286 C/T/A CRP polymorphism may be a contributing factor to the lower susceptibility to malaria seen in the Fulani." (PMID 19545442, 2009).